ERAP2 (endoplasmic reticulum aminopeptidase 2)
Diseases named in the same sentence as ERAP2 in open-access papers (continued):
Sharing a sentence is not in itself a finding about the gene and the disease.
Miscarriage (2 papers, 2021 to 2023). A pregnancy that ends at a stage in which the fetus is incapable of surviving on its own, defined as the spontaneous loss of a fetus before the 22th week of pregnancy. "The expression of ERAP1 and ERAP2 has been associated with other pregnancy complications, such as miscarriages." (PMID 36834865, 2023). "Clinical observations have further supported the relationship between ERAP2 and pregnancy complications, as miscarriages, PE, and other pregnancy-related complications are accompanied by an up-regulation of ERAP2." (PMID 36834865, 2023). "However, overexpression of ERAP2 (as in our patients with miscarriage) is unfavorable." (PMID 34745129, 2021). "Moreover, elevated levels of ERAP2, above 2.9 ng/ml, indicated a miscarriage." (PMID 34745129, 2021).
renal carcinoma (2 papers, 2022 to 2023). A carcinoma arising from the epithelium of the renal parenchyma or the renal pelvis. "In renal cancers, ERAP2 was found to be frequently downregulated compared to normal tissue, and potentially involved in immune escape mechanisms." (PMID 35804456, 2022).
endometrial cancer (1 paper, 2017). Primary or metastatic malignant neoplasm involving the endometrium (mucous membrane that lines the endometrial cavity). "The differential expression of ERAP1 and ERAP2 has been associated with several cancer types, including thyroid, lung, breast, colon, and endometrial cancers." (PMID 28977897, 2017).
gastritis (1 paper, 2025). Inflammation of the stomach. "When examining proteins correlated with the third component separating gastritis and preneoplasia, Capping Actin Protein of Muscle Z-Line Subunit a (CAPZA1), a-L-Fucosidase 2 (FUCA2), Endoplasmic Reticulum Aminopeptidase 2 (ERAP2), and LEP are found." (PMID 41155404, 2025).
Infertility (1 paper, 2021). "However, they did not detect any associations with PE for rs27044, rs26653, and rs26618 of ERAP1 and rs2248374 of ERAP2 as we did for RIF and infertility." (PMID 34745129, 2021).
lymphoblastic leukemia (1 paper, 2023). "Using a potent ERAP2 inhibitor, DG011A, to treat MOLT-4 lymphoblastic leukemia cells for selective ERAP2 inhibition, the study noted that the treatment induced significant shifts in the immunopeptidome." (PMID 36834865, 2023).
mantle cell lymphoma (1 paper, 2010). Mantle cell lymphoma is a rare form of malignant non-Hodgkin lymphoma affecting B lymphocytes in the lymph nodes in a region called the ``mantle zone''. "In ERAP2, NMD has been shown to degrade a rare mRNA form detected in a mantle-cell lymphoma that included an extra exon (after canonical exon 12) with an in-frame STOP codon." (PMID 20976248, 2010).
myeloma (1 paper, 2021). "One could speculate that the reduction of ERAP2 expression in myeloma cells could be beneficial by reducing their immunogenicity and leading to their increased survival by immune evasion." (PMID 33810334, 2021).
nasopharyngeal carcinoma (1 paper, 2020). A carcinoma arising from the nasopharyngeal epithelium. "EBV-encoded miRNAs have been reported to downregulate TAP1, TAP2, and ERAP2 mRNA in infected primary B cells, and the TAP2 mRNA was similarly reduced in EBV-associated nasopharyngeal carcinomas." (PMID 32098275, 2020).
pancreatic adenocarcinoma (1 paper, 2022). "used the risk score method to identify 3 genes associated with adverse prognosis of pancreatic adenocarcinoma (PAAD), ERAP2, CKLF and EREG, and constructed a nomogram based on clinical features and risk score for individualized prognosis prediction." (PMID 35757399, 2022).
pancreatic ductal adenocarcinoma (1 paper, 2023). An infiltrating adenocarcinoma that arises from the epithelial cells of the pancreas. "ERAP2 was associated with autophagy in pancreatic stellate cells (PSCs) within pancreatic ductal adenocarcinoma (PDAC)." (PMID 36834865, 2023).
papillary thyroid carcinoma (1 paper, 2019). "As for ERAP2, a multidisciplinary integrated analysis revealed its overexpression, along with other candidate genes, in papillary thyroid carcinoma (PTC) and the cystic fluid counterpart, pointing out a possible translocation from the canonical ER localization." (PMID 31379846, 2019). "Indeed, while ERAP1 secretion in the extracellular milieu has been thoroughly documented in immunocompetent cells and in murine macrophage cell lines, ERAP2 release has been reported only in the secretome of tumor cells derived from papillary thyroid carcinoma." (PMID 31379846, 2019).
renal cell carcinoma (1 paper, 2014). "In another study, expression of ERAP1 and ERAP2 was investigated in 300 normal kidney tissues and 334 renal cell carcinoma lesions." (PMID 25566501, 2014). "In renal cell carcinomas, ERAP1 and ERAP2 appear to have a different behavior, being the first more frequently up-regulated and the latter more frequently down-regulated, as compared to the normal counterpart." (PMID 25566501, 2014).
skin cancer (1 paper, 2025). "Six genes (RBM6, DNAJC18, SPIRE2, CPNE1, SEPT2, and ERAP2) presented causal associations with skin cancer." (PMID 41209561, 2025).
spondylitis (1 paper, 2024). The inflammation of a vertebra. "Furthermore, evidence of the distinctive influence of ERAP2 based on HLA binding specificities in Ankylosing Spondylitis studies suggests the likelihood of different HLA alleles and/or ERAP1 and 2 haplotypes in our study and other cohorts limits the ability to replicate results with existing data." (PMID 38980912, 2024).
Stroke (1 paper, 2025). Sudden impairment of blood flow to a part of the brain due to occlusion or rupture of an artery to the brain. "KO models for ERAP2 and SFXN4 indicated their involvement in immune regulation and iron metabolism, respectively, both processes implicated in stroke pathogenesis." (PMID 40777745, 2025).
cancer (41 papers, 2010 to 2025). A tumor composed of atypical neoplastic, often pleomorphic cells that invade other tissues. "Polymorphisms in the ERAP1 and ERAP2 genes have been associated with a range of cancers, as well, suggesting their involvement in tumor development and progression." (PMID 40226591, 2025). "The polymorphisms of the ERAP1 and ERAP2 genes play an important role in oncological pathology, and their expression is frequently modified in various forms of cancer, including lung, colon, prostate, kidney, bladder, cutaneous, and hematological cancers." (PMID 38534723, 2024). "As demonstrated here, ERAP1 and ERAP2 are associated with irregular peptides in the HLA system, several pregnancy complications, and cancers." (PMID 36834865, 2023). "Abnormal HLA peptides found in pregnancy and cancer are associated with ERAP2 expression." (PMID 36834865, 2023). "One study that linked the activity of ERAP2 to increased efficacy of immune checkpoint inhibitor cancer immunotherapy suggested that the pharmacological inhibition of ERAP2 could provide significant therapeutic implications." (PMID 36834865, 2023). "Impressively, reduced ERAP2 expression levels due to common genetic polymorphisms have been recently shown to predict survival in patients treated with ICI immunotherapy in 24 out of 24 cancer types examined." (PMID 35163832, 2022). "Recent studies have linked the activity of ER aminopeptidase 2 (ERAP2) to increased efficacy of immune-checkpoint inhibitor cancer immunotherapy, suggesting that pharmacological inhibition of ERAP2 could have important therapeutic implications." (PMID 35163832, 2022). "The low expression of ERAP2 has also been associated with poor cancer prognosis." (PMID 35804456, 2022). "This is supported by observations in cancer immunotherapy, where high ERAP2 expression (the risk haplotype for BU) is a strong prognostic predictor of poor survival in patients receiving checkpoint inhibitor therapy to induce T-cell mediated antitumor immunity." (PMID 33717175, 2021). "Collectively, this study provides further evidence for exploring mechanisms that could expand our knowledge of TCs in cancer and pregnancy, especially ERAP2-associated PE." (PMID 34445292, 2021). "Overall, ERAP1 and ERAP2 play crucial roles in cancer, affecting peptide processing and presentation on HLA molecules, thereby influencing the immune response to malignant cells." (PMID 38534723, 2024). "ERAP2 expression in cancer tends to be opposite to ERAP1, as ERAP2 deficiency is correlated with cancer growth through immune evasion." (PMID 36834865, 2023). "ERAP1 and ERAP2 are potential anti-cancer targets activating immune responses against malignant cancers by promoting T and NK cell-mediated cytotoxic responses." (PMID 36834865, 2023). "Studies in the transcriptional and post-transcriptional regulation of ERAP1 and ERAP2 have also been investigated in a cancer immunity setting." (PMID 36834865, 2023). "It is interesting that the same phenomenon was observed in some cancer cell lines expressing the “short” ERAP2, although the secretion appears to be specific for the MDMs." (PMID 35563348, 2022). "Given the importance of ERAP2 in immune evasion of cancer, potential clinical applications of its inhibitors have great prospects in tumor immunotherapy." (PMID 36214762, 2022). "ERAP1 is among the most conserved genes in WT cancers (SR = -2.797) and ERAP2 among the most conserved in mKRAS (SR = -2.085)." (PMID 36092893, 2022). "Both ERAP1 and ERAP2 have been shown to be downregulated in some cancers, play key roles in the shaping of the cellular immunopeptidome, and their activity has been associated with changes in anti-cancer immune responses." (PMID 33406696, 2021). "A recently developed potent ERAP1/ERAP2 inhibitor was successfully used to induce CTL responses against the cancer cells used in that study." (PMID 25566501, 2014).
cancer (continued). "Analysis of ERAP1 and ERAP2 expression by malignant cells has shown that the levels of these enzymes undergo significant changes that may correlate with the ability of cancer cells to evade immune responses." (PMID 38534723, 2024). "In addition to their involvement in the immune system, ERAP1, and ERAP2 also play a role in cell migration and angiogenesis, which are necessary for both pregnancy and cancer." (PMID 36834865, 2023). "In particular, the impacts of ERAP1 and ERAP2 on pregnancy and cancer should be explored further." (PMID 36834865, 2023). "Overall, research into the effects of ERAP1 and ERAP2 on pregnancy and cancer could yield a new understanding of the conditions and potential treatments for pregnancy complications and cancer, which affect many lives every day." (PMID 36834865, 2023). "The critical role of the ERAP1 and ERAP2 aminopeptidases in antigen processing presents a unique target to affect T cells responses with relevance to infection, autoimmunity, and immunosurveillance of cancer." (PMID 36569828, 2022). "Accordingly, ERAP2 has been shown to be upregulated in several cancers." (PMID 35163832, 2022). "Previous researcher has demonstrated that ERAP2 enzyme function could affect T cell and NK cell responses towards normal and cancer cells as well as the synthesis of inflammatory cytokines." (PMID 34992605, 2021). "ERAP2 could accelerate anti-tumor immune responses; hence, modulating the activity of ERAP2 may be a novel immunological strategy for cancer immunotherapy." (PMID 34143198, 2021). "Furthermore, endoplasmic reticulum aminopeptidases, ERAP1 and ERAP2, exhibit variable expression levels in different cancer types." (PMID 33406696, 2021). "ERAP1 and ERAP2 may be important targets that enhance T and NK cell-mediated immune responses against established cancers." (PMID 32596278, 2020). "This hypothesis comes from the observation that cancer patients with high ERAP2 expression showed worse overall survival after checkpoint inhibitor therapy (allowing T cells to kill cancer cells), relative to those with low ERAP2 expression." (PMID 33262772, 2020). "In the literature, genetic variants around ERAP2 have been associated with autoimmunity related disorders, whereas the ZSCAN9 gene is surrounded by the risk variants for neuropsychiatric diseases and cancer." (PMID 31244887, 2019). "For instance, it may be interesting to reassess previous studies of ERAP2 that used immortalized or cancer cell lines and reported contradictory results." (PMID 20976248, 2010). "Therefore, it is possible that pharmacological inhibition of ERAP2 could enhance the efficacy of cancer immunotherapy and extend it to more patients." (PMID 35163832, 2022). "However, as tumor cells are by definition genetically unstable and the cancer secretome may significantly differ from that of the physiological counterpart, to our knowledge this is the first report demonstrating ERAP2 secretion by immunocompetent cells." (PMID 31379846, 2019). "However, the understanding of ERAP2 roles in cancer cells, especially OSCC cells, remains limited." (PMID 28977897, 2017). "Indeed, the activities of ERAP for immune escape of cancer cells have been revealed, suggesting the poor survival of OSCC patients with elevated level of ERAP2 may result from the ERAP2-associated immune evasion." (PMID 28977897, 2017). "Altered expression of the ERAP2 gene may favor escape of cancer cells from immune surveillance." (PMID 25356585, 2014). "Similarly, using RNA-seq data, we found that a lower expression of APM-related genes, including B2M, CIITA, ERAP2, TAP2 and TAPBPL, was also associated with a shorter PFS, reflecting the increasing interest in APM biomarkers for clinical outcome and immune escape in cancer." (PMID 37799721, 2023). "Decreased ERAP2 expression weakens the activation of PSCs, tumor-PSC interactions, and the capacities of PSCs to promote cancer aggression." (PMID 37251940, 2023).
cancer (continued). "In cancer and autoimmune disorders, ERAP1 and ERAP2 are emerging molecules and double-edged swords regarding immune responses." (PMID 36834865, 2023). "A comparison of the similarities and differences between pregnancy and cancer and the roles ERAP1 and ERAP2 play in their progression is analyzed further." (PMID 36834865, 2023). "In addition to the possible role of the activity of ERAP1 and ERAP2 on the normal immune control of cancer, a series of recent studies have highlighted that these two enzymes may be important pharmacological targets for boosting immune responses to established cancers." (PMID 25566501, 2014). "In addition, 21 of these genes were eGenes almost universally across cancer types including five putative long non-coding RNAs, genes known to play a role in the immune response (ICOSLG, ERAP2) and U2AF1, which is involved in spliceosome function." (PMID 35725412, 2022). "According to previous studies, ERAP2 was closely related with CD8 T cell, NK cell, and several immune process, indicating it may play important roles in cancer immunology." (PMID 34992605, 2021). "These encouraging results, in the context of cancer, have shown that reducing ERAP1/ERAP2 activity can alter the immune response, which may well prove protective in AS and BSCR." (PMID 30054427, 2018). "The results presented here may suggest the important role for ERAP1 in the anti-cancer response, which is different in smokers versus never-smokers, depending to some extent on the presence of ERAP2, and affecting NSCLC clinical course." (PMID 34149699, 2021). "On the other hand, highly active ERAP1 without the presence of functional ERAP2, may appear to be suitable to produce cancer epitopes effectively recognized by immune cells capable of eliminating cancer cells." (PMID 34149699, 2021). "Our work suggests that, in cancer cells, ERAP2 plays important roles in limiting presentation of cancer antigens and thus pharmacological inhibition by DG011A or similar inhibitors may be a viable approach to modulating the cancer immunopeptidome for immunotherapy applications." (PMID 35163832, 2022).
tumor (30 papers, 2012 to 2025). "Many SNPs in ERAP1 and ERAP2 are associated with pregnancy complications such as pre-eclampsia or tumor risks." (PMID 36834865, 2023). "Inhibition of ERAP1 or ERAP2, can help reactivate such responses by protecting tumor-associated antigenic peptides from degradation." (PMID 33406696, 2021). "Since ERAP2 is deeply involved in the generation and destruction of immunopeptidome, its deficiency can lead to disorders in anti-tumor immunity activation." (PMID 34992605, 2021). "In the immune-evading tumor, malfunction ERAP2 can undermine tumor-associated antigenic episodes while the immune checkpoints are over-expressed, thus anti-tumor T cell response is suspended." (PMID 34992605, 2021). "An immune-evading tumor can be using ERAP1/ERAP2 to destroy tumor-associated antigenic peptides and over-expresses immune checkpoints such as PD-L1 to avoid T cell responses." (PMID 33406696, 2021). "Elevated ERAP2 expression was significantly associated with higher pN status, advanced overall stage, positive perineural invasion, and tumor depth (P = 0.041, 0.015, 0.010, and 0.032, respectively)." (PMID 28977897, 2017). "This process might influence tumor immunogenicity and immune infiltration, in which a deficiency of ERAP2 protein can contribute to immune evasion by tumor cells." (PMID 40622919, 2025). "However, while trimming peptides, ERAP2 can also destroy tumor-associated antigenic peptides destined for loading on MHC I, thus affecting avoiding T cell response." (PMID 34992605, 2021). "Importantly, overexpression of ERAP2 was associated with positive N stage, advanced overall stage, positive perineural invasion, and tumor depth (P = 0.041, 0.015, 0.010, and 0.032, respectively)." (PMID 28977897, 2017). "The results highlight the functional role of ERAP2 in tumor epitope presentation and TCR recognition." (PMID 38067336, 2023). "ERAP1 and ERAP2 trim peptides for antigen presentation on HLA class I molecules within the ER, which is crucial in tumor cell and immune system interactions." (PMID 36834865, 2023). "ERAP1 and ERAP2’s structure, location, and function implicate their potential impact on the irregular peptides, and HLAs found in trophoblast and tumor cells." (PMID 36834865, 2023). "ERAP2 also influenced the recognition of the gp100209–217 tumor epitope and enhanced T-cell recognition of the MART-126/27–35 epitope in the absence of ERAP1." (PMID 38067336, 2023). "The endoplasmic reticulum (ER) aminopeptidases ERAP1 and ERAP2 are two frequently altered genes that affect anti-tumor immune responses and tumor growth." (PMID 35418980, 2022). "Meanwhile, ERAP2 promotes tumor immune escape by helping to generate peptide ligands for MHC presentation." (PMID 36214762, 2022). "To validate the prognostic impact of ERAP2 on SqCLC, we established an independent SqCLC cohort, including a total of 190 SqCLC patients, and the tumor samples were retrospectively collected to constitute TMAs." (PMID 34992605, 2021). "We detected ERAP1 and ERAP2 expression in tumor cells and cells in the microenvironment in primary HL tissue samples." (PMID 33499248, 2021). "In our cohort, ERAP2 was significantly correlated with CD8+ tumor-infiltrating lymphocytes (TILs) (p=0.0029), and patients with higher ERAP2 expression had a higher percentage of PD-L1 positive patients (p=0.049) and a higher CD8+ TILs level (p=0.036)." (PMID 34992605, 2021). "One of the highlight conclusions of our study is that in both public data and our cohort, high expression of ERAP2 is correlated with the immunoreactive tumor microenvironment, which is favorable for administering immunotherapy in SqCLC." (PMID 34992605, 2021). "Animal model studies have shown that altered levels of ERAP1 and ERAP2 can facilitate tumor immune evasion." (PMID 29552294, 2018). "ERAP2 was highly expressed in the cytoplasm of tumor cells but was minimally detectable in the infiltrating lymphocytes and adjacent mesenchymal cells." (PMID 28977897, 2017).